IL4 (interleukin 4)
Diseases named in the same sentence as IL4 in open-access papers (continued):
Sharing a sentence is not in itself a finding about the gene and the disease.
co-infection (continued). "It was noteworthy that, the ratio of IFN-γ over IL-4 was sharply enhanced in co-infection group." (PMID 32295161, 2020). "Overall, this study provides fresh insight into the functional relationship between IFNγ- and IL-4-producing Th cells during co-infection and indicates that limiting acute Th1 responses may preserve Th2-mediated anti-helminth immunity." (PMID 26147567, 2015). "Indeed, in a mouse co-infection model of Nippostrongylus brasiliensis and Mtb, impaired immune defense against TB was dependent on IL-4 generation and subsequent alternative pathway activation." (PMID 24728010, 2014). "Our co-infection result is similar to mousepox virus expressing IL-4 which has increased virulence." (PMID 21139679, 2010). "Thus, to address whether the presence of large numbers of nematode expanded, tissue resident MΦ, in an M(IL-4) activation state, influenced bacterial induced recruitment of cells (gating strategy depicted in we established a consecutive co-infection model." (PMID 28334040, 2017). "Indeed we show, at baseline, that TB+HIV+ individuals displayed a different cytokine expression pattern when compared to TB+HIV− individuals, and co-infection was characterized by elevated IL-4, G-CSF, IFN-γ and TNF-α concentrations and decreased IL-12(p70) and IL-17 levels." (PMID 22606304, 2012). "Lower levels of CD4+ and CD8+ cells and higher level of IL4 and IL6 in patients on the day of admission were significantly correlated with the development of coinfection the following days in the hospital." (PMID 40416960, 2025). "Low but detectable increases in IL-1α, IL-4, MIP-1α, MIP-1β, TNF, fractalkine and RANTES occurred upon Mtb infection and Mtb/HIV-1 co-infection, depending of the cell type." (PMID 40420159, 2025). "and C. perfringens co-infection was highly correlated with IFN-α, IFN-γ, IL-4, IL-13, IL-16, LITAF, TGF-β4 and TNFSF15 in the jejunum, indicating that Th2 type cytokines mainly participated in avian NE." (PMID 37240767, 2023). "In this study, there was a significant decrease in the expression of IL-4 and IL-10 in patients with HIV/TB co-infection compared to patients with HIV monoinfection and TB monoinfection before ART." (PMID 34835417, 2021). "After co-infection (Ctrl + PRRSV-2/H3N2), TNF, IFN-γ, IL-12p40, IL-4 and CXCL-13 transcripts were all up-regulated (mean fold change of 2.43, 1.86, 3.47, 2.49 and 2.83, respectively)." (PMID 34858411, 2021). "Coinfection increased the percentage of CD4+, CD4+IL4+ and CD8+IL4+ cells and decreased TNF-α secretion after BCG stimulation in the spleen when compared with the BCG infection alone." (PMID 33936040, 2021). "This is in accordance with another study showing that T. muris evoked an increase in pro-inflammatory cytokines such as TNF-α along with an increase of IL-4 and IL-10 compared to BCG infection and co-infection." (PMID 28192437, 2017). "Compared with P. berghei ANKA-mono-infection group, the co-infection group showed a significantly lower level of IFN-γ on day 5 and day 8 pi and significantly higher levels of IL-4, IL-5 and IL-13 on day 3, 5, 8 pi." (PMID 24034228, 2013). "We find that helminth co-infection enhances Salmonella colonization of the small intestine even in mice which lack IL-4, Stat6, and RAG1, and also in mice lacking eosinophils, and bacterial microbiota-depleted mice." (PMID 33471793, 2021). "Those with Plasmodium mono-infection had higher levels of IL-4, IL-6, IL-10, IL-12, IL-13, IL-17A, IFN-γ, and MIP1-α/CCL3 compared with DENV mono-infection or co-infection; those with Plasmodium mono-infection had more cough than those with DENV mono-infection." (PMID 27128316, 2016). "We did not measure the IL-4δ2 splice variant which is an IL-4 antagonist and is increased in BAL cells in TB/HIV co-infection." (PMID 23527200, 2013). "Thus, co-infection of mice with KOS and two different recombinant viruses expressing IL-4, increased severity of CS in surviving mice." (PMID 21139679, 2010).
co-infection (continued). "Furthermore, during co-infection diminished, but not absent, Th2 cytokine secretion was observed and IL-4 and IL-13 were detectable after stimulation of splenocytes with killed STm." (PMID 25474738, 2014). "Mycobacterium bovis BCG co-infection, however, does not significantly impact Nb-induced IL-4 in the mesenteric lymph nodes; it would be of interest to know whether those lung-dwelling microparasites might have had similar effects to Pcc on Th2 responses, had they been measured in the TLN." (PMID 19951425, 2009). "The revealed reduced production of IL-4 and IL-10 indicates that despite the fact that patients with HIV/TB co-infection were in the late stages of the disease, they did not have a shift towards the expression of Th2 class cytokines." (PMID 34835417, 2021). "Compared to P. berghei-mono, mice in the co-infection-100c group had significantly lower levels of IFN-γ on days 5 and 8 pi and higher levels of IL-4, IL-5, IL-13 and TGF-β on days 3, 5, and 8 pi, while no significant changes in IL-10 levels were observed between the two groups." (PMID 24670210, 2014).
Cognitive impairment (51 papers, 2014 to 2025). Abnormal cognition is characterized by deficits in thinking, reasoning, or remembering. "For example, IL‐4‐producing T cells accumulated in the meninges of mice performing cognitive tasks, and loss of IL‐4 resulted in cognitive defects." (PMID 39692624, 2025). "Conversely, passive T cells transfer from WT mice into IL-4 deficient mice restored cognitive impairment and reduced the proinflammatory phenotype of meningeal myeloid cells." (PMID 37608988, 2023). "Furthermore, IL-4-deficient mice displayed a polarized proinflammatory meningeal myeloid cell phenotype and cognitive deficits." (PMID 37608988, 2023). "Interestingly, IL-4 plays an important role in cognition, since its impairment, caused by a lack of T cells that produce it or by the abolishment of IL-4R, is associated with cognitive impairment in learning tasks on the Morris water maze (MWM)." (PMID 39595890, 2024). "Interestingly, IL-4 function is associated with neuro-restorative effects after cerebral ischemic and traumatic brain injury events, while reduced IL-4 signaling is associated with cognitive impairments in schizophrenia." (PMID 35641947, 2022). "This review summarises and exposes the possible contribution of the imbalance between pro-inflammatory and anti-inflammatory interleukins like IL-1beta, IL-4 and TNFalfa among others on cognitive impairment." (PMID 39796167, 2025). "Animal studies have demonstrated that early-life overexposure to IL-4 reduces myelination, leading to cognitive deficits and developmental delays." (PMID 41462779, 2025). "These cytokines tend to decrease after chemotherapy, suggesting a potential protective role, especially for IL-4, against chemotherapy-related cognitive impairment." (PMID 41155372, 2025). "Recently, intranasal delivery of interleukin-4 (IL-4)-loaded lecithin-based liposomes was shown to enhance white matter integrity and attenuate long-term sensorimotor and cognitive deficits in MCAO models." (PMID 41304786, 2025). "In an amyloid precursor protein (APP) mouse model for AD—APP23, intracerebral injection of IL-4/IL-13 increases Aβ clearance and improves cognitive deficits." (PMID 39769453, 2024). "Longitudinal assessment of plasma IL-4 over 3 years also showed a decline in IL-4 levels over time in cognitive impaired patients." (PMID 38059210, 2023). "Many studies have shown that Th2 cells can reduce Aβ through an interleukin-4 (IL-4) dependent mechanism, thereby improving cognitive impairment." (PMID 36165328, 2022). "Several studies reported that reductions in IL-4 and IL-10 production markedly worsened cognitive impairment in AD patients and in the hippocampus of the Aβ1–42-injected rat model." (PMID 36359200, 2022). "In turn, cognitive impairment seems to correlate with peripheral levels of IL-1β, IL-4, IL-6 and IL-12, and considering only the AChR population, also with peripheral levels of TNF-α." (PMID 34501305, 2021). "The current review aims to elaborate on the possible role of IL-4 in epileptogenesis, epileptic development, and epilepsy-related cognitive impairment." (PMID 33013320, 2020). "IL-4−/− mice exhibited severe cognitive impairment and the level of pro-inflammatory CKs was increased." (PMID 33013320, 2020). "This is further supported by studies showing that T cell-derived IL-4 can modulate meningeal myeloid cells, increasing astrocyte expression of BDNF, associated with reduced cognitive deficits and neurodegeneration in a mouse model of tauopathy." (PMID 33173502, 2020). "IL-4 KO mice and T and B cell-deficient SCID mice have cognitive impairment in spatial learning tasks." (PMID 29872141, 2018). "Greater severity of cognitive impairment measured using the ACE-R and the MMSE was associated with having a significantly lower level of IL-1beta, IL-2 and IL-4, and a higher level of IL-6 and TNF-alpha." (PMID 29248892, 2018).
Cognitive impairment (continued). "Mice that lack IL-4 demonstrated cognitive impairment in spatial learning tasks; after transplantation with IL-4 competent bone marrow, this impairment was reversed." (PMID 24548288, 2014). "However, IL-4 was also found to be increased in plasma from patients with mild cognitive impairment, and interestingly, within this cohort lower levels of IL-4 were associated with worse PD motor impairment and worse cognitive testing." (PMID 38059210, 2023). "Here we proposed important ideas of IL‐1β, TNF‐α, and IL‐4; as the underlying CRCI pathway for coping with persistent psychological distress, as well as the potential evidence of psychological intervention to relieve cognitive impairment." (PMID 36965094, 2023). "Loss of IL-4 promotes the M1 phenotype in microglia/macrophages after ischemic stroke and exacerbates long-term sensorimotor dysfunction as well as cognitive deficits after ischemia, while infusion of IL-4 into the cerebroventricular after ischemic stroke improves neurological functions." (PMID 36339825, 2022). "Evidence from a previous animal study indicates that mice lacking IL-4 exhibited skewed proinflammatory meningeal myeloid cell phenotype and cognitive impairment in visuo-spatial learning tasks, which was reversed by transplantation of IL-4–competent bone marrow." (PMID 33301870, 2021). "Th2-mediated reversal of AD pathology may be IL-4-dependent, as IL-4–/– mice show cognitive impairments which are reversed upon the adoptive transfer of WT T cells." (PMID 33173502, 2020). "Nevertheless, this concept still requires further studies to show whether IL-4 can act as a cognitive protector in epilepsy-related cognitive impairment." (PMID 33013320, 2020). "Remarkably, IL-4 and IL-13 can activate microglia, the pivotal sources of inflammatory factors and oxidative stress in the brain, to induce Aβ degradation and improve cognitive impairment." (PMID 32382304, 2020). "Moreover, it has been suggested that cognitive task performance leads to the accumulation of IL-4–producing T cells in the meninges, and IL-4-null mice exhibit cognitive deficits." (PMID 28886095, 2017). "Treatment of cognitive impairment in AD patients with acetylcholinesterase inhibitors have also been found to decrease the production of pro-inflammatory cytokines and induced the secretion of the anti-inflammatory cytokine IL-4." (PMID 26142708, 2015). "Increasing evidence suggests that flavonoids could ameliorate allergic inflammation by suppressing IL-4 and IL-13 production following the release of basophils and histamine, and improve the cognitive impairment of patients with neurodegenerative disease by inhibiting TNF-α and IL-6 release." (PMID 37292198, 2023). "AYAC both during and post-chemotherapy had higher rates of self-perceived and objective cognitive impairment, lower plasma BDNF, and elevated IL-4, IL-6, IL-8, IL-10, and IFN-γ compared to NC during follow-up." (PMID 40597835, 2025). "Also, by restoring type 2 signaling through therapeutic injection of IL-33, IL-4 or IL-13, or augmenting hippocampal IL-4 with phosphatidyl serine, neurosynaptic function might be preventatively enhanced or bolstered in mild cognitive impairment or in early AD." (PMID 39071802, 2024). "Psychological distress was involved in chemotherapy‐related cognitive impairment (CRCI) by increasing IL‐1β, TNF‐α, and IL‐4 levels." (PMID 36965094, 2023). "Worsening cognitive impairment was correlated with a decrease in the cytokines IFN-γ, IL-1β, IL-2, IL-4, and IL-10." (PMID 37569491, 2023). "In addition to promoting M2 phenotype polarization, intranasal delivery of IL-4 nanoparticles poststroke also improves white matter integrity by acting directly on OPCs to enhance oligodendrocyte differentiation mediated by the PPARγ axis, which reduces long-term sensorimotor and cognitive deficits." (PMID 36339825, 2022).
Cognitive impairment (continued). "Upregulation of IL-4 expression in the hippocampus of APP/PS1 mice promoted β-amyloid (Aβ) clearance by microglia and ameliorated cognitive deficits." (PMID 35153675, 2021). "Background/Aims: We aimed to assess the association between in volumetric measures of hippocampal sub-regions – in healthy older controls (HC), subjects with mild cognitive impairment (MCI) and AD- with circulating levels of IL-4." (PMID 30705627, 2018). "Patients with mild cognitive impairment (MCI, n = 20) were found to have higher peripheral IL-4 compared to controls (n = 20), however increased dementia disease severity was associated with decreased plasma IL-4 potentially representing a more chronic inflammatory environment." (PMID 39526037, 2024). "In the absence of IL-4, the meningeal myeloid cells were skewed toward a proinflammatory phenotype, which resulted in cognitive impairment in IL-4 knockout mice." (PMID 28183352, 2017). "However, AST treatment remarkably lowered the IL-1β expression and enhanced IL-4 expression in the hippocampus and prefrontal cortex, indicating that the alleviation of AST in cognitive impairment may correlated with suppression of inflammatory response." (PMID 33208152, 2020). "Mice lacking IL-4 demonstrated cognitive impairment in a spatial learning task." (PMID 30413208, 2018). "Moreover, IFN-γ (P = 0.335) and IL-4 (P = 0.410) levels were similar between patients with and without cognitive impairment, but IL-17A was enhanced in patients with cognitive impairment compared to those without cognitive impairment (P < 0.001)." (PMID 36386524, 2022).
Insulin resistance (50 papers, 2012 to 2025). Increased resistance towards insulin, that is, diminished effectiveness of insulin in reducing blood glucose levels. "Proinflammatory cytokines produced by immune cells and secreted by the adipose tissue, such as TNF-α, IL-4, and IL-6, stimulate obesity-associated diseases, including insulin resistance, dyslipidemia, and cardiovascular diseases." (PMID 39204167, 2024). "Another study revealed that after adoptive transfer into obese Rag1-null mice, CD4+ T cells gained a Th2 profile, indicated by the production of IL-4 and IL-13, which was associated with reversal of enhanced weight gain and insulin resistance in recipient obese Rag1-null mice." (PMID 30459770, 2018). "In the adipose tissue, eosinophils are recognized as a source of IL-4 production, and eosinophil-deficient mice showed insulin resistance and impaired glucose tolerance under the HF diet condition, with a decrease of IL-4 production and number of M2a-subtype MΦs15." (PMID 30451856, 2018). "Some studies have correlated increased GDF-15 levels with increased IL-4 levels and insulin resistance." (PMID 39420932, 2024). "Downregulate M1-labeled mRNA induced by lipopolysaccharide in peritoneal macrophages, promote the expression of M2-labeled mRNA induced by IL-4, and alleviate insulin resistance and steatohepatitis." (PMID 37361209, 2023). "Study participants showed high waist circumference, adiposity, insulin resistance, dyslipidemia, pro-inflammatory adipokines and low anti-inflammatory factors like adiponectin and interleukin-4." (PMID 38004218, 2023). "Adipocytokines chemerin, AFABP (adipocyte-specific fatty acid-binding protein), interleukin-4 (IL-4), and interleukin-6 (IL-6) are enlisted in the regulation of insulin resistance and inflammation." (PMID 34007846, 2021). "Meteorin-like is a myokine associated with IL4, IL13, certain lymphocytes, decreased inflammation, and improved insulin resistance." (PMID 35126168, 2021). "Accordingly, we suggest although IL-4 exhibits pro-lipolytic activity under normal physiological condition, IL-4 alone is insufficient to improve energy homeostasis once insulin resistance had been developed." (PMID 31427606, 2019). "Nevertheless, insulin resistance takes the dominant role in muscle cells responding to IL-4 for maintaining homeostasis and avoiding cellular apoptosis or damage." (PMID 31814802, 2019). "The incompetency of long-term IL-4 injection to ameliorate insulin resistance is probably due to physical adaptation and/or compensation under consistent IL-4 exposure for meeting the in vivo energy requirements to maintain homeostasis." (PMID 31814802, 2019). "On the contrary, another study showed that adipocyte-specific CD1d1 deletion reduced IL-4 expression in adipose iNKT cells and increased AT inflammation and insulin resistance, in accordance with an earlier report." (PMID 29942311, 2018). "In obesity, the protective IL-4 production by iNKT cells is lost, and total iNKT cell numbers in AT and peripheral blood decrease, making leeway for adipose tissue inflammation, insulin resistance, and type 2 diabetes to develop." (PMID 29892305, 2018). "Functionally, AT-resident iNKT cells have an anti-inflammatory phenotype by secreting IL-4, which contributes to prevention of insulin resistance and AT inflammation." (PMID 29892305, 2018). "In mice, IL-4 treatment induces the M2-associated activation of ATMs, which in turn attenuates high fat diet (HFD)-induced insulin resistance." (PMID 26197341, 2015). "In the context of insulin action, M2 macrophages sustain insulin sensitivity by secreting IL-4 and IL-10, while M1 macrophages induce insulin resistance through the secretion of proinflammatory cytokines, such as TNFα." (PMID 23964268, 2013). "Taking these findings together, the activation of IL-4 signaling is considered to be a promising target to suppress insulin resistance and thus studies to identify molecular mediators are underway." (PMID 23964268, 2013).